G6PC3 (glucose-6-phosphatase catalytic subunit 3)
Diseases named in the same sentence as G6PC3 in open-access papers (continued):
Sharing a sentence is not in itself a finding about the gene and the disease.
breast carcinoma (1 paper, 2025). "Based on our observation that G6PC3 plays a role in genome maintenance and that mutations may contribute to familial breast cancer, we further investigated the potential tumor-suppressive function of G6PC3 in vivo in mammary epithelial cells." (PMID 40261702, 2025). "In conclusion, our cohort-based functional analysis has unveiled genome maintenance factors and identified G6PC3 as a potential candidate tumor suppressor in breast cancer." (PMID 40261702, 2025). "Consistently, G6PC3 depletion resulted in elevated γH2AX levels in breast cancer cell lines, including MCF7 and M.D. Anderson - Metastatic Breast 231 (MDA-MB-231)." (PMID 40261702, 2025). "We then investigated whether G6PC3 expression correlated with overall survival by analyzing its expression across different breast cancer hormone receptor subtypes with focus on BRCA1/2-intact patients." (PMID 40261702, 2025).
colitis (1 paper, 2020). Inflammation of the colon. "Hence, colitis in G6PC3 deficiency is attributed to haematopoietic cell defects, rather than intestinal epithelial or other non-haematopoietic cell defects." (PMID 31157858, 2020).
congenital heart disease (1 paper, 2018). A heart disease that is present at birth. "Mutations in G6PC3, which is located in the endoplasmic reticulum and catalyzes the dephosphorylation of glucose-6-phosphate, have recently been identified as resulting in autosomal recessive SCN with congenital heart disease." (PMID 30386760, 2018).
Hyperinsulinemia (1 paper, 2022). An increased concentration of insulin in the blood. "Many upregulated genes related to glucose metabolism were upregulated by hyperinsulinemia, such as G6pc3, Hk1, Pck2 and Aldoa, some of which were reverted to baseline by starvation." (PMID 34921686, 2022).
Insulin resistance (1 paper, 2021). Increased resistance towards insulin, that is, diminished effectiveness of insulin in reducing blood glucose levels. "The G6PC3 gene has genetically emerged as a new distinct gene showing its involvement in insulin resistance." (PMID 33669862, 2021). "The major outcome from the study was a unique gene ‘G6PC3’ showing upregulation in MHOW and still unknown for its existence in insulin resistance." (PMID 33669862, 2021). "However, in our study, in the MUNW group, G6PC3 has been downregulated, while upregulated in MHOW group suggesting its implication in nutrition-related pathways of insulin resistance." (PMID 33669862, 2021).
Kabuki syndrome (1 paper, 2023). Kabuki syndrome (KS) is a multiple congenital anomaly syndrome characterized by typical facial features, skeletal anomalies, mild to moderate intellectual disability and postnatal growth deficiency. "Hearing loss can be a clinical manifestation in patients with Kabuki Syndrome, glucose‐6‐phosphatase enzyme (G6PC3) deficiency, Reticular Dysgenesis, and ADA deficiency." (PMID 37102642, 2023).
non-alcoholic steatohepatitis (1 paper, 2025). "This state is reminiscent to non-alcoholic steatohepatitis (NASH) because of the downregulation of PPARα-related lipid metabolism and inhibition of glycogenesis (GYS2 down), which suggests glucose release or glycolysis (G6P and G6PC3 up, G6PD down)." (PMID 40806595, 2025).
Obesity (1 paper, 2013). Accumulation of substantial excess body fat. "Interestingly, a third group of genes (CPE, NPY5R, DRD3, TAS2R38, SLC18A1, G6PC3, NPY1R, and VLDLR) was highly associated with both neurological and obesity concepts." (PMID 23544116, 2013).
sarcoma (1 paper, 2025). A usually aggressive malignant neoplasm of the soft tissue or bone.
Severe congenital neutropenia type 4 (1 paper, 2012). "Severe congenital neutropenia type 4 (SCN4) is an autosomal recessive disorder caused by mutations in the third subunit of the enzyme glucose-6-phosphatase (G6PC3)." (PMID 23171239, 2012). "Severe congenital neutropenia type 4 (SCN4, OMIM# 612541) is caused by autosomal recessive mutations in G6PC3 on 17q21.31, which encodes one of the three subunits of the enzyme glucose-6-phosphatase." (PMID 23171239, 2012).
type 2 diabetes (1 paper, 2024). "Importantly, empagliflozin, a sodium-glucose cotransporter 2 (SGLT2) inhibitor frequently used to treat type 2 diabetes, has successfully resolved neutrophil defects in patients with G6PC3 deficiency by lowering the 1,5-AG blood concentrations." (PMID 39041036, 2024).
cancer (5 papers, 2020 to 2025). A tumor composed of atypical neoplastic, often pleomorphic cells that invade other tissues. "Besides its expanding role in neutrophil granulocytes as a metabolic repair enzyme, G6PC3 has been recently proposed to be linked to the progression and metabolic reprogramming of certain cancers." (PMID 39548727, 2025). "G6PC3 may have additional cancer-relevant roles, as it plays important roles in gluconeogenesis and glycogenolysis pathways." (PMID 40261702, 2025). "Our cancer genomic analysis based on the TCGA database indicate that G6PC3 mutations may be more relevant in familial rather than sporadic instances." (PMID 40261702, 2025). "By altering the self‐renewal capacity of tumor cells and potentially affecting chemotherapeutic responses, the G6PC3 phosphatase system and alternative substrate research may offer promising avenues for developing novel treatment strategies for this cancer type." (PMID 39548727, 2025). "However, there are no reported associations between G6PC3 gene mutations and cancer." (PMID 40261702, 2025). "The inconsistency between the expression level and the expected prognosis in the other five genes (RHPN1-AS1, MELK, EIF5AL1, and G6PC3: upregulated, but HR < 1; NLGN2: downregulated, but HR > 1) may be attributed to a protective response mechanism in order to resist the development of cancer." (PMID 32953881, 2020).
tumor (4 papers, 2023 to 2025). "Furthermore, loss of G6pc3 accelerated mammary tumorigenesis in mice, indicating a tumor-suppressor role for G6PC3 in vivo." (PMID 40261702, 2025). "G6PC3 was affluently expressed in the tumor with high 18F-FDG and 18F-FMISO accumulation." (PMID 38449509, 2024). "Given that GLUT1 expression had similar tendency, G6PC3 might have an important role in glucose metabolism affecting tumor aggressivity." (PMID 38449509, 2024).
autosomal recessive disease (2 papers, 2021). Autosomal recessive form of disease. "G6PC3 is well known for its expression in white blood cells, particularly neutrophils, and its deficiency leads to autosomal recessive disease SCN4 (severe congenital neutropenia type 4)." (PMID 33669862, 2021). "SCN4 is an autosomal recessive disease caused by mutations in the G6PC3 gene." (PMID 34305938, 2021).
bacterial infections (2 papers, 2013 to 2023). "We report a male patient with confirmed G6PC3 deficiency presented with recurrent bacterial infections and multi-systemic complications." (PMID 37296469, 2023). "Here we report a male patient with confirmed G6PC3 deficiency presented with recurrent bacterial infections and multi-systemic complications." (PMID 37296469, 2023). "Patients with G6PC3 deficiency usually present in the first few months of life with recurrent bacterial infections although a patient presenting with symptoms only in late teenage years has been described." (PMID 23758768, 2013).
genetic disorder (2 papers, 2024). "G6PC3 deficiency is a rare genetic disorder with a broad phenotypic spectrum, posing difficulties for timely diagnosis." (PMID 39041036, 2024).
G6PC3 also shares sentences with these, for which no sentence is quoted: infection (5 papers); Thrombocytopenia (4); leukemia (3); Crohn disease (2); cyst (2); Glycogen Storage Disease type Ib (2); CHARGE syndrome (1); cholangiocarcinoma (1); chronic granulomatous disease (1); Cohen syndrome (1); Cyclic neutropenia (1); gastric cancer (1); glycogen storage disease (1); glycogen storage disease type 1b (1); glycogen storage disease type I (1); Glycogen Storage Disease type Ia (1); Hypoglycemia (1); hypogonadotrophic hypogonadism (1); hypothyroidism (1); immune deficiency (1); Intellectual disability (1); lactic acidosis (1); leukocyte adhesion deficiency type II (1); lymphopenia (1); myeloid leukemia (1); nematode infections (1); oculocutaneous albinism (1); pulmonary hypertension (1); renal failure (1); Shwachman-Diamond syndrome (1).
A further 3 diseases each share a sentence with G6PC3 in 1 paper.